ADAMTS9 (ADAM metallopeptidase with thrombospondin type 1 motif 9)
Diseases named in the same sentence as ADAMTS9 in open-access papers (continued):
Sharing a sentence is not in itself a finding about the gene and the disease.
Insulin resistance (5 papers, 2009 to 2021). Increased resistance towards insulin, that is, diminished effectiveness of insulin in reducing blood glucose levels. "First, we investigated the association between cognitive aging and three insulin resistance-related genes, namely the ADAMTS9, GCKR, and PPARG genes." (PMID 28225792, 2017). "Along with our findings, evidence has been reported for an association of the ADAMTS9 gene with insulin sensitivity, insulin resistance, and T2D." (PMID 28225792, 2017). "Thus, we hypothesized that insulin resistance-associated genes, namely the ADAMTS9, GCKR, and PPARG genes, may be linked with cognitive aging." (PMID 28225792, 2017). "Among the genes involved in the development of insulin resistance are the ADAM metallopeptidase with thrombospondin type 1 motif 9 (ADAMTS9), glucokinase regulator (GCKR), and peroxisome proliferator activated receptor gamma (PPARG) genes." (PMID 28225792, 2017). "Downregulation of miR-190b by directly targeting IGF-1 and ADAMTS9 could regulate lipid metabolism and insulin signaling pathway in vitro and could reduce the hepatic steatosis and insulin resistance in vivo." (PMID 33768092, 2021). "Genes downregulated (n = 3) during the first ACTH response were associated with ECM remodeling and insulin resistance (ADAMTS9), cell growth and migration (ABI2), and negative regulation of tyrosine kinase activity (PTPN12)." (PMID 30804370, 2019).
melanoma (4 papers, 2008 to 2025). A malignant, usually aggressive tumor composed of atypical, neoplastic melanocytes. "Our analysis showed that EMT markers like N‐cadherin, ZEB1, ADAMTS9 and ITGA8, which were shown to regulate invasion in melanoma, where associated with low NRF2 target gene expression." (PMID 34951143, 2022). "Given that cell survival is an integral component of melanoma progression, ADAMTS9 and ADAMTS20 are excellent candidates for participating in melanoma." (PMID 18454205, 2008). "RT‐PCR analysis of melanoma cell lines A375 and A375 MEK after treatment with IC50 concentrations of KU757 confirmed the downregulation of CD20, CD25 and NDUFA7, as well as the upregulation of PRKCH, BMP2 and ADAMTS9 hub genes (p < 0.05)." (PMID 40135438, 2025). "Indeed, it resulted quite appealing the fact that such positive association did occur with high expression of other ADAMTS proteases (ADAMTS2, ADAMTS4, ADAMTS5, ADAMTS9, ADAMTS12 and ADAMTS14) that definitively implied a key role of these proteases during melanoma progression." (PMID 32230715, 2020).
nasopharyngeal carcinoma (4 papers, 2012 to 2020). A carcinoma arising from the nasopharyngeal epithelium. "Using a similar approach, ADAMTS9 was also shown to be down-regulated in nasopharyngeal carcinoma and was significantly associated with lymph node metastasis." (PMID 24213506, 2012). "However, ADAMTS9 acts as the tumor-suppressive gene in several human cancer cells, such as the process of tumor formation was suppressed in esophageal and nasopharyngeal carcinoma." (PMID 32744323, 2020). "In ESCC and Nasopharyngeal carcinoma (NPC), ADAMTS9 functions as a tumor suppressor, inhibiting tumor growth through suppressing angiogenesis." (PMID 24213506, 2012).
Arthritis (3 papers, 2012 to 2017). Inflammation of a joint. "Knockdown of Adamts9 expression using lentiviral shRNA in 3D chondrocyte culture resulted in an increase in matrix deposition and decrease in aggrecan degradation, suggesting an importance of Adamts9 in cartilage breakdown during pathological conditions such as arthritis." (PMID 24213506, 2012).
ciliopathies (3 papers, 2019 to 2025). "Phenotypes resembling human ciliopathies are also evident in Adamts9/Adamts20 double mutant mice (which survive to 15 days of gestation if they include the hypomorphic, but not the inactivated Adamts9 allele)." (PMID 40449594, 2025). "ADAMTS9 and ADAMTS20 are necessary for formation of the primary cilium, a cellular organelle of postmitotic cells that transmits signaling by hedgehog proteins and other morphogens, and recessive ADAMTS9 mutations were found in the human ciliopathies nephronophthisis and Joubert syndrome." (PMID 37169079, 2023).
Hypertension (3 papers, 2013 to 2024). The presence of chronic increased pressure in the systemic arterial system. "The ADAMTS9 gene has also been linked to hypertension, a common risk factor for kidney disease." (PMID 39143076, 2024). "Several gene regions identified in this study were near previously implicated hypertension genes (eg, GRM7, SLC4A7, ADAMTS9)." (PMID 26866891, 2016). "However, generalization of previously implicated hypertension (GRM7, SLC4A7, ADAMTS9) and SBP-associated loci (PLEKHA7) from cross-sectional analyses with much larger sample sizes, provide strong evidence that these statistical models are robust." (PMID 26866891, 2016).
ischemic stroke (3 papers, 2017 to 2023). A stroke disorder caused by obstruction of blood flow to the brain, due to thrombotic (local blood clot formation) or embolic (due to a blood clot or other material traveling from another site) event. "A growing body of evidence further indicates that the ADAMTS-9 protein, which is encoded by the ADAMTS9 gene, may be involved in physiological conditions and pathological disease states in central nervous system injuries such as ischemic stroke and spinal cord injury." (PMID 28225792, 2017).
osteoarthritis (3 papers, 2023 to 2025). A noninflammatory degenerative joint disease occurring chiefly in older persons, characterized by degeneration of the articular cartilage, hypertrophy of bone at the margins and changes in the synovial membrane. "Among them, ADAMTS9 belongs to the hub enzyme of proteoglycan degradation, and its harmful role in osteoarthritis, rheumatoid arthritis, and intervertebral disc degeneration have been widely described." (PMID 37481583, 2023). "Nevertheless, our data can be used to design small molecule inhibitors for other pharmaceutical targets, for example ADAMTS4 and ADAMTS5 in osteoarthritis, ADAMTS7 in atherosclerosis, or ADAMTS8 in pulmonary arterial hypertension, which spare ADAMTS9." (PMID 40449594, 2025).
atherosclerosis (2 papers, 2023 to 2025). A disease characterized by the build-up of fatty material and calcium deposition in the arterial wall resulting in partial or complete occlusion of the arterial lumen. "In this study, we aimed to evaluate subclinical atherosclerosis in obese patients with CVD risk indicators such as arterial stiffness (assessed by PWV measurement) and CIMT as well as serum biomarkers of endothelial dysfunction such as endocan, ADAMTS7, and ADAMTS9." (PMID 37252704, 2023).
cleft palate (2 papers, 2018 to 2019). Cleft palate is a fissure type embryopathy that affects the soft and hard palate to varying degrees. "Adamts20Bt/Bt mice have a low incidence of cleft palate, but upon deletion of one Adamts9 allele, they have fully penetrant cleft palate and further reduction in pigmented hair follicles." (PMID 30814516, 2019). "In fact, several of the Shh target genes identified here in the cNCC, including Adamts9, Edn1, Dlg1, and Efnb1, are already implicated in cleft palate pathogenesis by existing mouse models." (PMID 29945554, 2018). "Adamts9Gt/Gt embryos also had cleft palate, and further Adamts9 dosage reduction via combination of Adamts9Gt with the inactivating Adamts9Del allele (Adamts9Gt/Del) resulted in failure to undergo rotation, an open neural tube and death by E10.5." (PMID 30814516, 2019).
colon cancer (2 papers, 2017 to 2024). "The genes analyzed in this study, Chromosome 18 open reading frame 8 protein (C18ORF8/RMC1) and a disintegrin and metalloproteinase with thrombospondin motifs 9 (ADAMTS9) have been highlighted for their association with colon cancer tumors." (PMID 39058128, 2024). "The ADAMTS9 gene encodes a member of the ADAMTS family of proteins which are involved in the control of organogenesis during the development and inhibition of angiogenesis in studies conducted on colon cancer." (PMID 39058128, 2024).
colorectal cancer (2 papers, 2020 to 2023). A primary or metastatic malignant neoplasm that affects the colon or rectum. "Especially, functional annotation showed that rs7623129 overlapped with the enhancer histone mark and DNAse hypersensitivity site, indicating that it may be involved in the development of colorectal cancer by regulating the expression of nearby ADAMTS9." (PMID 36694225, 2023).
coronary artery disease (2 papers, 2020 to 2024). "In addition, the nearest genes or expression quantitative loci (eQTL) genes in seven loci were previously associated with SU-associated traits, such as ADAMTS9 associated with coronary artery disease and MBL1P associated with COPD23,24." (PMID 38658550, 2024).
esophageal squamous cell carcinoma (2 papers, 2012 to 2019). Esophageal squamous cell carcinoma (ESCC) is a type of esophageal carcinoma (EC) that can affect any part of the esophagus, but is usually located in the upper or middle third. "Next, decreased extracellular protease ADAMTS9 plays anti-angiogenic and tumor suppressive functions, e.g., in esophageal squamous cell carcinoma." (PMID 31717665, 2019). "The first report of ADAMTS9 being a tumor suppressor was reported in esophageal squamous cell carcinoma (ESCC) using somatic cell hybridization and critical region analysis." (PMID 24213506, 2012).
lung carcinoma (2 papers, 2020 to 2025). "Both ADAMTS6 and ADAMTS9 gene expression is reduced in lung cancer, which may potentially be associated with the role of the genes as tumor suppressors." (PMID 39940703, 2025). "Adamts9 was reported as a tumor suppressor which could inhibit tumor growth and angiogenesis in various cancers including lung cancer." (PMID 32370197, 2020). "In the first stage of the analysis, the mRNA expression of the ADAMTS6, ADAMTS9, and ADAMTS12 genes was assessed in lung cancer, and the obtained results were compared with data from adjacent normal tissues." (PMID 39940703, 2025). "The greatest number of differences between normal and lung cancer samples was observed for the ADAMTS12 gene (n = 110); these changes were considerably more frequent than in ADAMTS6 and ADAMTS9 (DMRs: n = 7 and n = 10, respectively)." (PMID 39940703, 2025).
nephronophthisis (2 papers, 2023 to 2024). Progressive tubulointerstitial injury, inherited in an autosomal recessive pattern, caused by mutations in genes involved in ciliary function, which may result in an end stage renal failure. "ADAMTS9 has been implicated in the pathogenesis of juvenile nephronophthisis and nephronophthisis, two pathological conditions." (PMID 39143076, 2024).
pulmonary arterial hypertension (2 papers, 2024 to 2025). Pulmonary arterial hypertension (PAH) is a group of diseases characterized by mean pulmonary artery pressure >20 mmHg and elevated pulmonary arterial resistance leading to right heart failure. "The KCNK3 and ADAMTS9 genes have been implicated in cardiac function, with KCNK3 identified as a predisposing factor for pulmonary arterial hypertension (PAH), primarily affecting atrial function and playing roles in rhythm regulation and cardiac conduction." (PMID 39596121, 2024).
thyroid cancer (2 papers, 2022 to 2025). "Additionally, for most charted tumor types, ADAMTS9 gene expression was significantly higher in normal tissues than in the associated tumor samples, and overexpression of the ADAMTS9 gene was observed only in thyroid carcinoma (THCA), CHOL, COAD, KIRP, LIHC, and STAD." (PMID 39940703, 2025). "First, we verified the expression of 9 immune-related prognostic factors, AKAP12, APOC1, TIMP3, ADAMTS9, ANK2, HTRA3, SYNDIG1, ​​ADAMTS5 and DACT1, in 11 thyroid cancer cell lines in the CCLE database." (PMID 36591507, 2022).
acne vulgaris (1 paper, 2024). "The biological annotation analysis indicates that we have identified 3 pairs of associated genes between gut microbiota and acne vulgaris, including PLA2G4A/FADS2, TIMP3/ADAMTS9 and ZC3H3/CPSF4L." (PMID 38371936, 2024). "After conducting biological annotation, we identified six genes (PLA2G4A, FADS2, TIMP17, ADAMTS9, ZC3H3, and CPSF4L) that may be associated with the pathogenic gut microbiota of acne vulgaris patients." (PMID 38371936, 2024).
aging (1 paper, 2017). A developmental process that is a deterioration and loss of function over time. "Here, we report for the first time that the ADAMTS9 gene may play a key role in the modulation of cognitive aging for the elderly in a Taiwanese population." (PMID 28225792, 2017).
bladder cancer (1 paper, 2020). "In conclusion, high expression of ADRA2A, CXCL12, S1PR1, ADAMTS9, F13A1, and SPON1 was associated with poor overall survival in bladder cancer patients, with a P-value <0.05 considered to be statistically significant." (PMID 32239176, 2020).
breast tumours (1 paper, 2018). "In this study, we show for the first time that ADAMTS9 is epigenetically silenced in both BC cell lines and primary breast tumours, but remains unmethylated in normal breast tissues and cells." (PMID 29193730, 2018).
central obesity (1 paper, 2024). "Studies have identified several genes associated with central obesity and IFG, including ADAMTS9, TBX15-WARS2, and DNM3-PIGC." (PMID 38917085, 2024).
chondrosarcoma (1 paper, 2020). A malignant cartilaginous matrix-producing mesenchymal neoplasm arising from the bone and soft tissue. "Inflammatory-responsible elements have been detected and characterized in the ADAMTS-9 gene promoter using chondrocytes and chondrosarcoma cells, which caused an increase in ADAMTS-9 levels in the presence of proinflammatory cytokines such as IL-1β." (PMID 32150898, 2020).
Corneal opacity (1 paper, 2016). A reduction of corneal clarity. "We report here that haploinsufficiency of murine Adamts9, encoding a secreted metalloproteinase with 15 TSRs, leads to congenital corneal opacity and Peters anomaly (persistent lens-cornea adhesion), which is a hallmark of PPS." (PMID 27687499, 2016).
endometrial cancer (1 paper, 2023). Primary or metastatic malignant neoplasm involving the endometrium (mucous membrane that lines the endometrial cavity). "In another study, a statistically significant decrease in ADAMTS9 was found in patients with endometrial polyps compared with patients with endometrial cancer." (PMID 36982551, 2023).
esophageal cancer (1 paper, 2019). A primary or metastatic malignant neoplasm involving the esophagus. "Functional importance of ADAMTS9 in nasopharyngeal and esophageal cancers has been described." (PMID 30959550, 2019).
female infertility (1 paper, 2021). Diminished or absent ability of a female to achieve conception. "Further studies are required to elucidate the processes and mechanisms of Adamts9 at late time points that could lead to male biased sex ratio, abnormal ovary, and female infertility reported in Adamts9 KO24." (PMID 33879810, 2021).
glioma (1 paper, 2022). A benign or malignant brain and spinal cord tumor that arises from glial cells (astrocytes, oligodendrocytes, ependymal cells). "Among them, ADAM9, ADAM12, ADAMTS7, ADAMTS9, and ADAMDEC1 were the proteases where increased expression associated with poorer prognosis of glioma patients." (PMID 36172139, 2022).
glomerular diseases (1 paper, 2023). "To investigate whether ADAMTS9 dysfunction causes NPHP and glomerulopathy, we differentiated ADAMTS9 knockout human induced pluripotent stem cells (hiPSCs) into kidney organoids." (PMID 37035301, 2023). "Since ADAMTS9 is speculated to have proteolytic activity intracellularly that plays an important role in ciliogenesis, further studies are needed to confirm that the proteolytic activity of ADAMTS9 is necessary for the development of glomerular diseases." (PMID 37035301, 2023).
heart malformations (1 paper, 2015). "Adamts9-null mice die prior to gastrulation, but hemizygous Adamts9+/− mice have heart malformations that reflect decreased detection of the DPEAAE neo-epitope and resulting accumulation of intact versican." (PMID 26025392, 2015).
joint disease (1 paper, 2019). "Our results suggest that unlike ADAMTS-4 and ADAMTS-5, which are widely recognised as destructive aggrecanases in joint disease, the aggrecanolytic activity of ADAMTS-9 might be more important for normal joint development than for pathology." (PMID 30699963, 2019).
Joubert syndrome-related disorders (1 paper, 2023). "Homozygous frameshift variants (p.Gln1525Hisfs*60) of ADAMTS9 have been associated with severe brain anomalies and renal dysfunction, whereas compound heterozygous mutations (p.Arg647Gln and p.Arg1203Trp) have been observed in Joubert syndrome-related disorders without any renal dysfunction." (PMID 37035301, 2023).
keratoconus (1 paper, 2023). A degenerative, structural disorder of the eye, characterized by a cone-shaped protrusion of the cornea. "Thus, variants associated with keratoconus have been detected in ADAMTS9." (PMID 37895187, 2023).
lymph node metastasis (1 paper, 2012). "Promoter hypermethylation and association of lower levels of ADAMTS9 protein with lymph node metastasis in NPC." (PMID 24213506, 2012).
microphthalmia (1 paper, 2023). Congenital or developmental anomaly in which the eyeballs are abnormally small. "Interestingly, genes involved in microphthalmia (VAX1, ALDH1A3, GJA1, and SMOC1) and retinal dystrophies (ADAMTS9, KCNJ13, CA2 and ABCA4) were also selected." (PMID 37479765, 2023).
migraine (1 paper, 2023). "However, the molecular mechanisms underlying ADAMTS9’s effect on insulin action and migraine risk are currently unknown." (PMID 36808568, 2023).
non-small cell lung carcinoma (1 paper, 2025). A group of at least three distinct histological types of lung cancer, including non-small cell squamous cell carcinoma, adenocarcinoma, and large cell carcinoma. "This study aimed to evaluate the methylation levels of the ADAMTS6, ADAMTS9, and ADAMTS12 genes in non-small-cell lung cancer (NSCLC) using data from bioinformatics databases." (PMID 39940703, 2025).
pancreatic cancers (1 paper, 2017). "A significant correlation between ADAMTS9 methylation and loss of expression of ADAMTS9 was observed in gastric, colorectal and pancreatic cancers by real-time PCR." (PMID 28406917, 2017).
Peters anomaly (1 paper, 2016). Peters anomaly (PA) is a congenital corneal opacity disorder characterized by a central corneal leukoma that obstructs the pupil leading to visual loss as well as absence of the posterior corneal stroma and Descemet membrane. "We demonstrate here that congenital corneal opacity and Peters anomaly results from Adamts9 haploinsufficiency in mice." (PMID 27687499, 2016).
polycystic ovary syndrome (1 paper, 2024). A disorder that manifests as multiple cysts on the ovaries. "In a study on polycystic ovary syndrome, it was found that the level of IL-17A in patients was negatively correlated with ADAMTS9." (PMID 38371936, 2024).
psoriatic arthritis (1 paper, 2023). Joint inflammation associated with psoriasis. "Also, variants in the ADAMTS9 gene, involved in the cartilage extracellular matrix, are found to be associated with psoriatic arthritis." (PMID 37628670, 2023).
septal defects (1 paper, 2006). "ADAM genes identified in this study have previously been associated with ventricular septal defects and valvular defects (ADAM19), fibrotic eye disease (ADAMTS9), disrupting angiogenesis (ADAMTS8), and cell adhesion (ADAM 28)." (PMID 16948840, 2006).